OTC (ornithine transcarbamylase)
Description:
Catalyzes the second step of the urea cycle, the condensation of carbamoyl phosphate with L-ornithine to form L-citrulline. The urea cycle ensures the detoxification of ammonia by converting it to urea for excretion.
Synonyms: OTCase; OTCD; OTC1; OCTD
Tractability: Small molecule: a structure with a bound ligand is known; it has a high-quality binding pocket; it belongs to a druggable protein family. PROTAC: its protein half-life has been measured; a small molecule that binds it is known.
Target class: Enzyme; Transferase
Gene: Protein-coding gene on chromosome X (38,327,598 to 38,424,632, forward strand). Ensembl gene ENSG00000036473.
Subcellular location: Mitochondrion matrix
Subcellular location (Human Protein Atlas): Mitochondria
Pathways (Reactome):
Disease: OTC leader sequence variants cause OTC deficiency; OTC main chain variants cause OTC deficiency
Metabolism: Urea cycle
Protein localization: Mitochondrial protein import
Gene Ontology:
Molecular function: ornithine carbamoyltransferase activity; amino acid binding; carboxyl- or carbamoyltransferase activity; identical protein binding; phosphate ion binding; phospholipid binding
Biological process: ammonium homeostasis; citrulline biosynthetic process; L-ornithine catabolic process; urea cycle; amino acid metabolic process; liver development; midgut development; monoatomic anion homeostasis; response to biotin; response to insulin; response to nutrient levels; response to xenobiotic stimulus; response to zinc ion
Cellular component: mitochondrial matrix; mitochondrion; cytosol; mitochondrial inner membrane
Gene-disease validity (ClinGen):
ClinGen rates the evidence that OTC causes each of these diseases.
ornithine carbamoyltransferase deficiency (X-linked): Definitive. Ornithine transcarbamylase deficiency (OTCD) is a disorder of urea cycle metabolism and ammonia detoxification characterized by either a severe, neonatal-onset disease found almost exclusively in males, or later-onset (partial) forms of the disease.
Homologues: Orthologues: chimpanzee OTC (99% identical), dog OTC (97% identical), macaque OTC (94% identical), pig OTC (94% identical), mouse Otc (93% identical), rat Otc (92% identical), guinea pig OTC (90% identical), rabbit OTC (90% identical), tropical clawed frog otc (75% identical), zebrafish otc (68% identical). Paralogues in human: CAD (30% identical), CPS1 (24% identical).
Diseases named in the same sentence as OTC in open-access papers:
OTC is named in the same sentence as 172 diseases in open-access papers, as found by Europe PMC text mining. Sharing a sentence is not in itself a finding about the gene and the disease. The quoted sentences say what the papers report.
Hyperammonemia (46 papers, 2010 to 2026). An increased concentration of ammonia in the blood. "As an X-linked enzyme, OTC breaks down citrulline in mitochondria, and pathogenic variant can lead to dangerously high levels of ammonia (hyperammonemia) and glutamine (hyperglutaminemia) in the blood." (PMID 41123737, 2025). "The modulation of the β‐catenin/c‐Myc axis was further investigated in a spf‐ash mice, a genetic model of OTC (ornithine‐transcarbamylase enzyme) deficiency and an in vivo model of hyperammonemia." (PMID 39798123, 2025). "The main reason is that the OTC gene variants lead to the loss or decrease of OTC enzyme function, which hinders the ammonia conversion to urea, resulting in hyperammonemia and severe neurological dysfunction." (PMID 39039447, 2024). "Defects in the OTC gene cause an impairment in ureagenesis, resulting in hyperammonemia, which is a direct cause of brain damage and death." (PMID 37628367, 2023). "Deficiencies in OTC are the most common urea cycle disorder in humans who present with hyperammonemia." (PMID 37343102, 2023). "Complete deficiency of OTC enzyme is mostly detected in hemizygous males, presents with severe episodes of hyperammonemia in the neonatal period and causes neurodevelopmental disability and high mortality." (PMID 37626723, 2023). "Metabolic studies were suggestive of hyperammonemia secondary to ornithine transcarbamylase (OTC) deficiency triggered due to fasting prior to the strabismus surgery." (PMID 35949797, 2022). "If left untreated, severe mutations in OTC can lead to life-threatening episodes of hyperammonemia and central nervous system damage in the neonatal period and throughout life." (PMID 33484963, 2021). "The two male siblings (P5 and P6) with the same mutation in the OTC gene presented similarly except the exact onset time of their first hyperammonemia episode." (PMID 32934962, 2020). "We demonstrated HDR-based correction of a G-to-A mutation in 10% of OTC alleles in the livers of newborn spfash mice, which provide a model of chronic hyperammonemia, and clinical benefits following in vivo genome editing." (PMID 32095520, 2020). "Ornithine transcarbamylase (OTC) deficiency is an X-linked recessive disorder that leads to hyperammonemia and liver damage." (PMID 31662921, 2019). "Ornithine transcarbamylase deficiency is the most common of the urea cycle disorders and frequently presents with coma or seizures during hyperammonemia." (PMID 30007405, 2018). "Ornithine transcarbamylase deficiency (OTCD), an X-linked disorder that results from mutations in the OTC gene, causes hyperammonemia and leads to various clinical manifestations." (PMID 30175132, 2018). "Genetic variants in this gene including missense, nonsense and frameshift mutations as well as deletions and duplications in this gene results in ornithine transcarbamylase deficiency, which causes hyperammonemia." (PMID 29554876, 2018). "Since OTC activity measured in a liver biopsy sample was within normal limits, OTC deficiency was initially excluded from the differential diagnoses of hyperammonemia." (PMID 23829977, 2013). "The diagnosis included an inherited metabolic disease - urea cycle disorder (ornithine transcarbamylase (OTC) deficiency) - accompanied by hyperammonemia, neonatal seizures, depression of central nervous system (CNS) functions, and disseminated intravascular coagulation (DIC) with gastric bleeding." (PMID 41246763, 2025). "It is believed that patients with the mutated OTC gene can develop hyperammonemia at any stage." (PMID 36128655, 2022). "Sodium phenylbutyrate has been used to treat patients with defects in ornithine transcarbamylase (OTC), a mitochondrial enzyme involved in the synthesis of citrulline, with measurable improvements in clinical symptoms associated with hyperammonemia and hyperglutaminemia." (PMID 36293464, 2022).
Hyperammonemia (continued). "The mouse-bearing mutation in the OTC gene, a hereditary hyperammonemia model, showed significant loss of cholinergic neurons, and the cholinergic neurons were damaged by ammonia in vitro culture, suggesting a direct toxic effect of ammonia on cholinergic neurons." (PMID 35736461, 2022). "Notably, gene correction in adult OTC-deficient mice was lower and was accompanied by larger deletions that ablated the residual expression of the endogenous OTC gene, leading to diminished protein tolerance and lethal hyperammonemia on a chow diet." (PMID 37894981, 2023). "The consequent reduction of mitochondrial ornithine levels diminishes the activity of OTC, resulting in elevated carbamoyl phosphate levels and subsequent hyperammonemia." (PMID 40710547, 2025). "Due to the mild hyperammonemia, Sanger sequencing of the OTC gene was performed to exclude heterozygous ornithine transcarbamylase deficiency (OTC deficiency), but no pathogenic variant was detected." (PMID 37510312, 2023). "Ornithine transcarbamylase (OTC) deficiency, a urea cycle disorder, is a rare congenital metabolic error that leads to hyperammonemia." (PMID 36827025, 2023). "In terms of underlying mechanisms that may cause toxicity, OTC-mutated mice showed elevated levels of tryptophan, a precursor for serotonin and serotonin metabolite, and altered expression of brain serotonin receptors, implying a disturbed serotoninergic system by hyperammonemia." (PMID 35736461, 2022). "At present, it is generally believed that environmental stress factors cause an increase in nitrogen catabolism load, which produces a negative nitrogen balance in patients and further diminishes already overburdened OTC activity, leading to hyperammonemia." (PMID 36128655, 2022). "It has been revealed that the inadequacy of the OTC enzyme synthesis in humans triggers frequent and life-frightening events of hyperammonemia." (PMID 34977000, 2021). "The spfash OTC mouse model recapitulates the hyperammonemia commonly seen in patients when stressed with a high protein diet, due to residual levels of OTC activity (~5%) in these mice." (PMID 28238287, 2017). "Valproate administration has also been shown to trigger acute hyperammonemia in patients with no underlying metabolic issues, and to unmask OTC deficiency in heterozygous females." (PMID 41550690, 2026). "Furthermore, the YWHAZP10 gene is located next to OTC and CASK, the deletion of which results in hyperammonemia and X-linked intellectual disability, respectively." (PMID 38674334, 2024). "As OTC-deficient Spfash mice exhibit a mild phenotype without severe hyperammonemia episodes, the main therapeutic outcome is the correction of orotic aciduria." (PMID 37626723, 2023). "Affected animals had 5% residual OTC activity and could survive on a chow diet; however, they developed hyperammonemia, which can be lethal when fed a high-protein diet." (PMID 37894981, 2023). "To elucidate the mechanism of hyperammonemia induced by corticosteroid administration in OTCD patients, we analyzed a mouse model by administering corticosteroids to OTCspf−ash mice deficient in the OTC gene." (PMID 35346058, 2022). "His mother was a heterozygote for the OTC gene and developed acute hyperammonemia during pregnancy." (PMID 32934962, 2020). "An OTC-deficient male and a CPS1-deficient female survived from episodes of hyperammonemia." (PMID 32934962, 2020). "A postchemotherapy hyperammonemic encephalopathy emulating OTCD has been described as a distinct syndrome of hyperammonemia in two young women with hepatocellular carcinoma, who resulted mutation-negative to OTC." (PMID 25026867, 2014). "Moreover, recurrent moderate hyperammonemia was observed, that is thought to represent mild OTC deficiency, although a causative OTC (OMIM *300,461) variant has not been identified." (PMID 37198333, 2023).
Hyperammonemia (continued). "One limitation has been demonstrated in this study, in which an editing vector capable of rectifying one mutation would not be appropriate for patients holding various OTC mutations, plus the expression would not be quickly sufficient to remedy a hyperammonemia disorder." (PMID 34977000, 2021). "However, an editing vector able to correct one mutation would not be applicable for patients carrying different OTC mutations, plus expression would not be fast enough to treat a hyperammonemia crisis." (PMID 32095520, 2020). "Indeed, alterations in cognitive functioning seen in asymptomatic OTC carriers suggest that other factors besides hyperammonemia may play a role." (PMID 25647322, 2015). "Hepatic protein expression of the UCEs, OTC, CPS1, and GLUD1 were significantly down-regulated in hyperammonemia, which was restored upon treatment with OP and TAK-242." (PMID 40053595, 2025). "The decreased levels of OTC in FLC and coincident observations of hyperammonemia mirror the build-up of ammonia seen in cases of genetic OTC deficiency." (PMID 37343102, 2023). "Complete absence of OTC activity is commonly observed in hemizygous males, resulting in severe hyperammonemia during the neonatal period." (PMID 40710547, 2025). "In addition to hyperammonemia, the presence of orotic acid in the urine is a characteristic surrogate marker of OTCD because accumulated carbamoyl phosphate, a substrate for OTC, enters the pyrimidine nucleotide synthesis pathway, which produces orotic acid." (PMID 33484963, 2021). "Downregulated expression of OTC together with other urea cycle enzymes also occurs in non-alcoholic steatohepatitis, where it leads to hyperammonemia." (PMID 34658931, 2021). "Since the proper functioning of OTC is essential to avoid hyperammonemia, it is not surprising to find OTC also in other tissues." (PMID 34658931, 2021). "Therefore, because of the slow kinetics of OTC expression, the gene correction approach would not be suitable to treat patients with OTC during the acute phase of hyperammonemia, although it would have long-lasting effects after the initial phase after treatment." (PMID 32095520, 2020).
urea cycle disorder (36 papers, 2011 to 2026). A genetic inborn error of metabolism characterized by the deficiency of one of the enzymes necessary for the urea cycle. "Ornithine transcarbamylase deficiency (OTCD), a rare hereditary disease caused by gene mutation of ornithine transcarbamylase (OTC), is the most prevalent type among urea cycle disorders." (PMID 39328593, 2024). "This method has been used in a DMS study to assess the functional effects of over 1500 SNV-accessible single amino acid substitutions in the human OTC gene, which encodes ornithine transcarbamylase and is linked to the most prevalent urea cycle disorder." (PMID 38940340, 2024). "We reported the variants of CPS1, ASS, ASL and OTC detected in the patients with urea cycle disorders through a nation-wide survey in Japan." (PMID 36303552, 2022). "Low-normal creatine levels have been reported in urea cycle disorders, with lower values in OTC and ASS deficiency compared with ASL deficiency." (PMID 34471603, 2021). "A recent study on plasma of urea cycle disorders (UCD) identified novel altered compounds in partial ornithine transcarbamylase (OTC) deficiency disease (X linked UCD) in female participants." (PMID 31640247, 2019). "Although a rare disorder, ornithine transcarbamylase deficiency is the most common of the urea cycle disorders, which can occur both in children, and less commonly, in adults." (PMID 26593089, 2015). "Being known as Buphenyl® or triButyrate® in the US or Ammonaps® in Sweden, it is used as a medication against urea cycle disorders involving deficiencies of carbamylphosphate synthetase, ornithine transcarbamylase, or argininosuccinic acid synthetase." (PMID 22723850, 2012). "Ornithine transcarbamylase (OTC) deficiency is the most common urea cycle disorder." (PMID 40206416, 2024). "Ornithine transcarbamylase (OTC) deficiency (OTCD) is an X-linked urea cycle disorder." (PMID 38053928, 2023). "In addition, rare cases of urea cycle disorders, especially ornithine transcarbamylase deficiency have been reported in patients with nonsyndromic ASD." (PMID 21760924, 2011). "Ornithine transcarbamylase (OTC) deficiency (OMIM #311250) is the most common urea cycle disorder (UCD), affecting approximately 1 in 56 000 to 1 in 113 000 individuals." (PMID 41550690, 2026). "Orotic acid levels, which are elevated in OTC (ornithine transcarbamylase) deficiency (OMIM #: 311250), were normal in our patient, making this particular urea cycle disorder less likely." (PMID 37927481, 2023). "Ornithine transcarbamylase (OTC) deficiency (OTCD) [MIM: 311250] is an X-linked defect of ureagenesis and the most common urea cycle disorder (UCD)." (PMID 38053940, 2023). "Urea cycle disorders (UCD): Deficiency of enzymes converting ammonia to urea, most common being ornithine transcarbamylase deficiency (OTCD)." (PMID 35453911, 2022). "Six of the 61 patients with small molecule disorders had a urea cycle disorder (CPS1, OTC, and ASL deficiencies)." (PMID 36101823, 2022). "Ornithine transcarbamylase deficiency (OTCD) is an X‐linked urea cycle disorder characterised by reduced or absent OTC enzyme activity, resulting in the accumulation of neurotoxic ammonia." (PMID 35822098, 2022). "Much research has been motivated by OTC deficiency, a complete or partial lack of OTC that causes the most common urea cycle disorder in humans." (PMID 34658931, 2021). "OTC splicing mutations are generally associated with the severest and early disease onset of ornithine transcarbamylase deficiency (OTCD), the most common urea cycle disorder." (PMID 33228018, 2020). "CPS1, carbamoyl phosphate synthetase 1; NAGS, N-acetylglutamate synthase; ORNT1, ornithine translocase; OTC, ornithine transcarbamylase; UCD, urea cycle disorders." (PMID 37480106, 2023). "Ornithine transcarbamylase (OTC) deficiency (OTCD) [MIM: 311250] is an X-linked defect of ureagenesis and the most common urea cycle disorder (UCD), accounting for about half of the reported patients." (PMID 36362876, 2022).
urea cycle disorder (continued). "ASL, argininosuccinate lyase; ASS, argininosuccinate synthase; CPS, carbamoyl phosphate synthase I; i.v., intravenous; OTC, ornithine transcarbamylase; UCD, urea cycle disorder." (PMID 32269302, 2020). "In the case of valproate, pharmacogenetic testing is helpful for certain genes, i.e., POLG, OTC, and CSP1, when a mitochondrial disorder or a urea cycle disorder is suspected." (PMID 36873203, 2023). "Four genes (OTC, ASL, CPS1, and ASS1) were responsible for urea cycle disorders, accounting for 14.6% (13/89)." (PMID 34733806, 2021). "ASL, argininosuccinate lyase; ASS, argininosuccinate synthase; CPS, carbamoyl phosphate synthase I; NKRT, non-kidney replacement therapy; OTC, ornithine transcarbamylase; UCD, urea cycle disorder." (PMID 32269302, 2020).